ING1 (inhibitor of growth family member 1)
Diseases named in the same sentence as ING1 in open-access papers (continued):
Sharing a sentence is not in itself a finding about the gene and the disease.
melanoma (5 papers, 2006 to 2021). A malignant, usually aggressive tumor composed of atypical, neoplastic melanocytes. "Decreased ING1 expression or loss of heterozygosity of the ING1 locus have been observed in various tumors, including breast, ovarian, head carcinomas and melanoma." (PMID 21767350, 2011). "On the other hand, reduced nuclear ING1 expression was associated with a much higher mutation rate (20%) of the ING1 gene in human primary melanomas." (PMID 16755297, 2006). "For instance, ING1 missense mutations in the Sin3-associated polypeptide 30 (SAP30) interacting region 102 (R- > L) or at the end of PHD zinc finger codon 260 (N- > S) reduced ING1 activity for nucleotide excision DNA repair in melanoma cells." (PMID 34685579, 2021). "LOH in tumor suppressor inhibitor of growth 1 (ING1) is associated with carcinogenesis in human non-small cell lung cancer, and deletion in the neurofibromin 1 (NF1) gene promotes formation of malignant melanoma." (PMID 25493073, 2014).
acute pancreatitis (4 papers, 2006 to 2024). An acute inflammatory process that leads to necrosis of the pancreatic parenchyma. "The human-engineered and humanized antibodies, ING-1 and 3622W94, demonstrated higher affinity (approximately 0.16–0.19 nM) but were associated with severe toxicities, including acute pancreatitis." (PMID 39595576, 2024). "From the present in-vitro data, the induction of acute pancreatitis by mAbs 3622W94 and ING-1 is best explained by their high binding affinities for EpCAM seen in Biacore analyses, in particular their very slow off-rates." (PMID 21044305, 2010). "All showed much higher in vitro cytotoxic activity than edrecolomab, but the two high-affinity antibodies ING-1 and 3622W94 turned out to be much less tolerable than edrecolomab due to induction of acute pancreatitis." (PMID 16404366, 2006).
non-small cell lung carcinoma (4 papers, 2006 to 2021). A group of at least three distinct histological types of lung cancer, including non-small cell squamous cell carcinoma, adenocarcinoma, and large cell carcinoma. "miR-500 promotes non-small cell lung cancer proliferation, migration, and invasion by targeting ING1." (PMID 34676206, 2021).
pancreatic cancer (4 papers, 2014 to 2025). "Researchers have found that overexpression of miR-371-5p downregulates growth inhibitor 1 (ING1) and leads to increased pancreatic cancer cells proliferation and tumor growth." (PMID 35651786, 2022). "Recent studies have revealed that elevated levels of miR-371-5p result in the downregulation of inhibitor of growth family member 1 (ING1), leading to the enhanced proliferation of pancreatic cancer cells and subsequent tumor growth." (PMID 40227591, 2025).
glioma (3 papers, 2013 to 2023). A benign or malignant brain and spinal cord tumor that arises from glial cells (astrocytes, oligodendrocytes, ependymal cells). "However, it is not completely clear how NTZ-associated autophagy influences the inhibition of glioma growth, even with ING1 degradation." (PMID 30302016, 2018). "Subsequently, we confirmed that NTZ reduced glioma cell viability by upregulating ING1-induced cell cycle arrest in glioma, which illustrates the core role of ING1 in NTZ treatment." (PMID 30302016, 2018). "To assess the clinical correlation between ING1 expression and prognosis of glioma patients, we performed survival analysis of glioma RNA-seq data separated into high and low ING1 level groups according to the mean expression in TCGA database." (PMID 30302016, 2018). "Our results demonstrated that chloroquine synergistically enhanced the chemosensitivity of glioma cells toward NTZ by the inhibition of ING1 autophagic degradation, which suggests a novel therapeutic strategy for clinical treatment of glioma." (PMID 30302016, 2018). "This indicates that ING1 might regulate HDAC1 expression beyond an epigenetic mechanism under the context of NTZ in glioma, which should be confirmed in further studies." (PMID 30302016, 2018). "Increased transcriptional activity and decreased degradation may both enhance ING1 expression in glioma." (PMID 30302016, 2018). "All these results show that NTZ induces G0/G1 phase arrest by upregulating ING1 in glioma." (PMID 30302016, 2018). "Thus, we hypothesized that NTZ predominantly exerts its pharmacological function in glioma cell cycle arrest by upregulating ING1." (PMID 30302016, 2018). "However, whether the association between ING1 and HDAC1 exists in glioma, or even after NTZ treatment has not been investigated nowadays." (PMID 30302016, 2018).
lung carcinoma (3 papers, 2006 to 2019). "In 2011, an interesting study was carried out by Luo and colleagues, investigating the role of ING1 in lung carcinoma." (PMID 31390718, 2019). "Notably, there is very limited data available on the effect of ING3 in lung cancer, whereas the function of ING1, ING2, ING4, and ING5 has been investigated in lung cancer in more detail." (PMID 31390718, 2019). "Summing up these findings, ING1 and ING2 are evidently expressed differentially in human lung cancer, as compared to healthy lung tissue." (PMID 31390718, 2019).
lymphoma (3 papers, 2011 to 2021). A malignant (clonal) proliferation of B- lymphocytes or T- lymphocytes which involves the lymph nodes, bone marrow and/or extranodal sites. "Knockout experiments demonstrated that ing1-dificient mice were more sensitive to total body gamma radiation, and loss of ing1 was associated with earlier onset and higher incidence of lymphomas." (PMID 21052543, 2011). "Interestingly, deletion of all Ing1 isoforms in CJ-7 mouse strain predisposes animals to lymphomas, suggesting that Ing1 is indeed a tumour suppressor." (PMID 33925563, 2021). "Investigations in transgenic mouse models have so far seemed to confirm that Ing1 and Ing2 are tumour suppressor genes, respectively preventing lymphomas and soft-tissue sarcomas." (PMID 33925563, 2021). "Genetic deletion of the Ing1 locus in a mouse model leads to early onset and increased incidence of lymphomas." (PMID 29381681, 2018).
osteosarcoma (3 papers, 2012 to 2016). A usually aggressive malignant bone-forming mesenchymal neoplasm, predominantly affecting adolescents and young adults. "Since ING1 enhanced paclitaxel- and etoposide-induced apoptosis in osteosarcoma cells, we asked if ING1b could also enhance toxicity of 5azaC and the third generation HDAC inhibitor LBH589." (PMID 22916295, 2012).
brain cancer (2 papers, 2013 to 2017). A primary or metastatic malignant neoplasm affecting the brain. "Altered localization of ING1 in brain cancers and its shuttling from the cytoplasm to nucleus by interaction with 14-3-3 proteins are consistent with ING proteins functioning in multiple cell compartments." (PMID 28511652, 2017). "Some of examples include that ING1 proteins are aberrantly localized to the cytoplasm in brain cancer, and that eukaryotic initiation factors 2alpha and 4E are frequently localized in the nucleus of meningiomas and in the same compartment of the oligodendroglial tumors, respectively." (PMID 23761452, 2013).
esophageal cancer (2 papers, 2011 to 2023). A primary or metastatic malignant neoplasm involving the esophagus. "However, the identified candidate genes within this region, such as RB1, BRCA2, and ING1, seldom show mutations in esophageal cancer, implying that other unknown tumor-suppressor genes within this region might participate in the tumorigenesis of this cancer." (PMID 22174605, 2011).
fibrosarcoma (2 papers, 2011 to 2020). A malignant mesenchymal fibroblastic neoplasm affecting the soft tissue and bone. "ING1 also binds H3K4me3, and this binding is somehow necessary for ING1-mediated DNA repair upon UV irradiation as well as doxorubicin-mediated induction of apoptosis in HT1080 fibrosarcoma cells." (PMID 21052543, 2011).
progeria (2 papers, 2017 to 2019). "Indeed, impaired DNA demethylation in Gadd45a/Ing1 double-knockout mice has been shown to lead to a segmental progeria phenotype." (PMID 31156709, 2019).
prostate carcinoma (2 papers, 2021 to 2022). A carcinoma that arises from epithelial cells of the prostate gland. "ING1's role as a tumor suppressor gene (TSG) has been demonstrated in a variety of human cancers including lung cancer, colorectal cancer, prostate cancer, and astrocytoma." (PMID 36056353, 2022). "Overall, ING1 and 2 are identified as AR-corepressors inhibiting androgen signaling, while ING3 is known to act as AR-coactivator playing role in prostate cancer pathogenesis." (PMID 36056353, 2022).
soft tissue sarcoma (2 papers, 2018 to 2019). A malignant neoplasm arising from muscle tissue, adipose tissue, blood vessels, fibrous tissue, or other supportive tissues excluding the bones. "Similarly, the Ing2−/− animals have a threefold higher incidence of soft-tissue sarcomas, providing concrete evidence that at least Ing1 and Ing2 are bona fide tumour suppressors." (PMID 29381681, 2018).
ameloblastoma (1 paper, 2019). The most common odontogenic tumor, arising from the epithelial component of the embryonic tooth and usually affecting the molar-ramus region of the mandible or maxilla. "Knockout of some of the ING genes in murine models by various groups has verified their status as tumor suppressors, with ING1 knockout resulting in the formation of large clear-cell B-lymphomas and ING2 knockout increasing the frequency of ameloblastomas, among other phenotypic effects." (PMID 31752342, 2019).
diabetes (1 paper, 2025). "Compared to the STEMI cohort, myocardial infarction (MI) patients with diabetes exhibited reduced expression of Rapgef5 and elevated expression of Ing1." (PMID 40162308, 2025). "Diabetes aggravates post-MI remodeling via Rapgef5/Ing1-mediated apoptosis and proliferation, these findings highlight novel therapeutic targets for diabetic cardiovascular complications." (PMID 40162308, 2025). "Among these, two data points aligned with the RNA sequencing results, revealing downregulation of the Rapgef5 genes and upregulation of the Ing1 gene in cardiac tissues of patients with diabetes mellitus complicated by myocardial infarction." (PMID 40162308, 2025). "In addition, we have found that Rapgef5 and Ing1 are involved in diabetes-mediated cardiomyocyte apoptosis and proliferation following myocardial infarction." (PMID 40162308, 2025). "In addition, our extensive examination of human samples has conclusively demonstrated that diabetes significantly modulates the expression of genes (Rapgef5 and Ing1) within the cardiac tissue of individuals afflicted with STEMI, underscoring the intricate interplay between these conditions." (PMID 40162308, 2025). "Conversely, Ing1 expression was markedly upregulated in the cardiac tissue of STEMI patients with diabetes compared to those without diabetes." (PMID 40162308, 2025).
diffuse large B-cell lymphoma (1 paper, 2025). "This work also shows that like animals lacking ING1, loss of ING5 results in the development of diffuse large B-cell lymphomas, confirming its status as a type II tumor suppressor." (PMID 39787145, 2025).
gallbladder cancer (1 paper, 2025).
Hypertension (1 paper, 2012). The presence of chronic increased pressure in the systemic arterial system. "Taking the first and last genes in the list as examples, for each term (i.e., MDM2 and ING1 for apoptosis, and REN and ACE2 for hypertension), we found strong evidence in the most recent supporting publications for linking these non-gold standard genes to the query." (PMID 23282288, 2012).
influenza infection (1 paper, 2024). "During influenza infection in the absence of the IFN-α/ß receptor, inflammatory and apoptotic responses may be initiated via induction of Ing1, Nr4a1, Polr2a, or Hoxa13." (PMID 38902760, 2024).
myocardial infarction (1 paper, 2025). Gross necrosis of the myocardium, as a result of interruption of the blood supply to the area, as in coronary thrombosis. "Based on the available search results, the mechanistic roles of Rapgef5 and Ing1 in diabetic myocardial infarction (MI) remain underexplored." (PMID 40162308, 2025).
retinoblastoma (1 paper, 2013). A malignant tumor that originates in the nuclear layer of the retina. "An age-associated isoform of ING1, ING1a, induces cell senescence by altering endocytosis, subsequently activating the retinoblastoma tumor suppressor." (PMID 23472054, 2013).
triple-negative breast carcinoma (1 paper, 2014). An invasive breast carcinoma which is negative for expression of estrogen receptor (ER), progesterone receptor (PR), and human epidermal growth factor receptor 2 (HER2). "We next evaluated the ability of ING1 to regulate migratory and invasive behavior of the MDA-MB231 triple negative breast cancer cell line." (PMID 24962136, 2014).
tumor (50 papers, 2000 to 2026). "They employed subtractive hybridization based on a polymerase chain reaction (PCR) technique and then screening the tumor suppressor genes, cloned a newly discovered gene they termed ING1 with a 33 kDa-encoded protein." (PMID 36056353, 2022). "Specifically, low stromal ING1 expression was associated with tumor grade and size, i.e. patients with lower expression of stromal ING1 had better prognosis." (PMID 26306560, 2015). "The in vitro and in vivo assays showed that overexpression of miR-371-5p resulted in cell proliferation and increased tumor growth, which was associated with inhibitor of growth 1 (ING1) downregulation." (PMID 25411783, 2014). "We also observed that an increase in total tumor ING1 protein levels is associated with a concomitant rise in cytoplasmic ING1 levels in OSCC samples." (PMID 24912621, 2014). "Down regulation and mislocalization of ING1 have been reported in diverse tumor types and Ser/Thr phosphorylation has been implicated in both of these processes." (PMID 23585863, 2013). "The loss of ING1 caused tumor growth of pre-neoplastic mammary epithelial cells in nude mice, whereas the presence of ING1 inhibited growth and transformation." (PMID 23585863, 2013). "Similar to p15PAF, p33ING1b is a PCNA-interacting protein, and is an isoform encoded by the ING1 tumor suppressor locus." (PMID 23593430, 2013). "Intriguingly, cancer-associated mutations in the ING1 PHD domain impaired the binding of ING1 to H3K4me3 with concomitant loss of functions in DNA repair and apoptosis, implying that the binding of ING1 to H3K4me3 underlies its tumor-suppressive functions." (PMID 21052543, 2011). "As this observation of association of stromal ING1 with patient survival was unanticipated for a typical type-II tumor suppressor, we wanted to determine the underlying reason for association of higher stromal ING1 expression with poor prognosis of patients in the luminal group of the cohort." (PMID 26306560, 2015). "Overexpression of ING1 caused cell cycle arrest at G1 phase with ensuing apoptosis, whereas suppression of its expression increased colony focus formation and growth in vitro and tumour formation in vivo." (PMID 25411783, 2014). "In addition, we found that Src could functionally antagonize the ability of ING1b to induce apoptosis, suggesting that Src may promote tumour survival by reducing ING1 levels and causing ING1 relocalization." (PMID 23585863, 2013). "Over two decades ago, groundbreaking work identified ING1 as a tumour suppressor, and as such most studies of ING proteins have focused on their cancer-protective potential." (PMID 33925563, 2021). "The INhibitor of Growth family was defined in the mid-1990s by the identification of a tumour suppressor, ING1, and subsequent expansion of the family based essentially on sequence similarities." (PMID 33925563, 2021). "Missense mutations in the PHD motif of ING1 and ING4 abolished their tumour suppressive nuclear function." (PMID 34685579, 2021). "The INhibitor of Growth (ING) family of proteins was founded when in 1996 ING1 was identified as a tumour suppressor, a protein that prevents cancer development." (PMID 33925563, 2021). "ING1 is a type II tumour suppressor with well-established roles in the transcriptional regulation of genes that control cell proliferation, response to DNA damage, oncogene-induced senescence and apoptosis." (PMID 34493070, 2021). "ING1 plays a role in epigenetic regulation as tumor suppressor, being a stoichiometric member of histone acetlytransferase (HAT) and histone deacetylase (HDAC) complexes." (PMID 32290470, 2020). "Consistent with function as a tumor suppressor, ING1 knockdown in vitro promoted neoplastic transformation." (PMID 31752342, 2019). "The survival analysis suggests that ING1 serves as a tumor suppressor with a prognostic role in GBM patients." (PMID 30302016, 2018).